GLB1L (galactosidase beta 1 like)
Description:
Cleaves beta-linked terminal galactosyl residues from gangliosides, glycoproteins, and glycosaminoglycans.
Synonyms: MGC10771
Tractability: Antibody: UniProt places it where antibodies can reach, with high confidence; UniProt predicts a signal peptide or a membrane-spanning region; its Gene Ontology location is reachable by antibodies, with medium confidence.
Gene: Protein-coding gene on chromosome 2 (219,236,598 to 219,245,478, reverse strand). Ensembl gene ENSG00000163521.
Pathways (Reactome):
Metabolism: CS/DS degradation; Glycosphingolipid catabolism; Keratan sulfate degradation
Gene Ontology:
Molecular function: beta-galactosidase activity; hydrolase activity, hydrolyzing O-glycosyl compounds
Biological process: galactose catabolic process; carbohydrate metabolic process
Cellular component: vacuole
Genetic constraint (gnomAD): Loss-of-function variants: 55 observed, 78.9 expected, observed/expected ratio (o/e) 0.7, 90% interval 0.56 to 0.87. The upper end of that interval is the gene's LOEUF score, 0.87, which puts it in group 3 of 6, group 1 being the genes least tolerant of losing a copy. Missense variants: 795 observed, 844.71 expected, observed/expected ratio (o/e) 0.94, 90% interval 0.89 to 1. Synonymous variants: 296 observed, 321.86 expected, observed/expected ratio (o/e) 0.92, 90% interval 0.83 to 1.01.
Homologues: Orthologues: chimpanzee GLB1L (99% identical), macaque GLB1L (97% identical), pig GLB1L (87% identical), rabbit GLB1L (87% identical), dog GLB1L (85% identical), guinea pig GLB1L (83% identical), mouse Glb1l (80% identical), rat Glb1l (79% identical), tropical clawed frog glb1 (55% identical), zebrafish glb1l (54% identical), Drosophila melanogaster Ect3 (40% identical), Drosophila melanogaster Gal (37% identical), and 2 more. Paralogues in human: GLB1 (53% identical), GLB1L2 (35% identical), GLB1L3 (32% identical).
Diseases named in the same sentence as GLB1L in open-access papers:
GLB1L is named in the same sentence as 3 diseases in open-access papers, as found by Europe PMC text mining. Sharing a sentence is not in itself a finding about the gene and the disease. The quoted sentences say what the papers report.
tumor (1 paper, 2021). "The expression of GLB1L and TMEM265 was associated with the level of tumor-infiltrating immune cells (r > 0.4, p < 0.05)." (PMID 34692486, 2021). "We also found that the expression levels of GLB1L and MLF1 were downregulated in tumor tissues relative to normal tissues, which suggested that both of them influence tumor initiation and progression in NPC." (PMID 34692486, 2021).
GLB1L also shares sentences with these, for which no sentence is quoted: cancer (1 paper); melanoma (1).